RNU7-141P (RNA, U7 small nuclear 141 pseudogene)
Gene: Small nuclear RNA gene on chromosome 20 (59,852,667 to 59,852,728, reverse strand). Ensembl gene ENSG00000238777.
Homologues: Orthologues: chimpanzee U7 (100% identical), macaque U7 (97% identical). Paralogues in human: RNU7-28P (87% identical), RNU7-143P (85% identical), RNU7-35P (85% identical), RNU7-7P (85% identical), RNU7-45P (84% identical), RNU7-60P (84% identical), RNU7-67P (84% identical), RNU7-13P (82% identical), RNU7-18P (82% identical), RNU7-22P (82% identical), RNU7-34P (82% identical), RNU7-57P (82% identical), and 142 more.